CRP (C-reactive protein)
Diseases named in the same sentence as CRP in open-access papers (continued):
Sharing a sentence is not in itself a finding about the gene and the disease.
infection (continued). "Among the control patients who had negative blood cultures, four patients had no infection verified and were not treated by antibiotics and their plasma C-reactive protein at the time of blood culture sampling ranged 13–101 mg/L." (PMID 28235076, 2017). "Within the patients’ group, eight subjects with wound complications (e.g., infection) had higher CRP levels (average ~35 mg/L) than the subjects without complications (average ~9 mg/L)." (PMID 29257113, 2017). "In this study we have assessed plasma vitamin C concentrations in critically ill patients relative to infection status (septic shock or non-septic) and level of inflammation (C-reactive protein concentrations)." (PMID 29228951, 2017). "The levels of PCT and CRP of the infection group were significantly higher than those of the non-infection group and the normal control group before treatment, and the difference had statistical significance (P<0.05)." (PMID 28811772, 2017). "This deduction cannot be reinforced by our data due the lack of a suitable marker of infection and limitations of CRP." (PMID 28441968, 2017). "Except for day 6, there were no statistical differences in daily CRP values or peak CRP between the groups with and without infection." (PMID 28201980, 2017). "The level of PCT of the infection group was remarkably higher than that of the non-infection group after treatment (P<0.05), but the difference of CRP level between the infection group and non-infection group had no statistical significance (P>0.05)." (PMID 28811772, 2017). "CRP is a nonspecific protein present in acute-phase inflammation and also reacts to infection and tissue injury." (PMID 29137033, 2017). "Despite its routine clinical use, few studies have examined the CRP concentration as a biomarker of infection in critically ill patients, and the results have not been consistent." (PMID 28226029, 2017). "In a cohort of 3,340 patients after cardiac surgery (5.6% infection rate), those patients with infection showed significantly decreased 1,25(OH)D levels and higher CRP levels, while 25(OH)D was not reduced." (PMID 28079172, 2017). "It has been shown that CRP offers no advantage over PCT to diagnose infection following liver transplantation." (PMID 28201980, 2017). "Serum PCT and C-reactive protein (CRP) appear to be useful to rule out infection or monitor therapy." (PMID 28484510, 2017). "After dividing countries by infection burden, we were able to apply inflammation adjustments only for CRP and SF concentrations because of the lack of AGP data in low– and medium–infection-burden countries (Colombia, Mexico, and the United States)." (PMID 29070567, 2017). "It is worth noting that the correlation between A-FABP4 plasma levels and plasma IL-6 and CRP persisted in patients without infections." (PMID 28500294, 2017). "Despite that the presentation of impending shock, her infection markers including white cell count and C-reactive protein were not raised." (PMID 28886185, 2017). "Previous studies suggest that patients with infectious respiratory symptoms and a CRP below this 20 mg/L threshold are likely to have non-bacterial, or self-limited infections." (PMID 28991170, 2017). "Conversely, when infection was defined using CRP only, all covariates were non-significant with the exception of baseline ferritin concentration." (PMID 27391972, 2016). "We found no relation between sCD59 and general markers of infection, including CRP and neutrophil counts." (PMID 27215188, 2016). "No patients had a suspected co-existing infection at time of injury, but they presented elevated C-reactive protein levels and white blood cells counts (>12,000/μl in 13/15 patients), indicative of a systemic inflammatory response." (PMID 27936199, 2016). "From a diagnostic perspective, we reasoned that TNF-α should distinguish between patients with SIRS and without SIRS (non-SIRS) while CRP should perform best at distinguishing infection (VAP) from no infection (non-VAP)." (PMID 28469676, 2016).
infection (continued). "It is unclear if infection or other disease states influenced higher SF values as CRP was not measured." (PMID 26891320, 2016). "Our results support the implementation of clinically guided CRP testing to help rule out serious infection and the need for hospital admission." (PMID 27716201, 2016). "Acknowledging this relationship, we included CRP as a candidate predictor variable, although this was a healthy population without clinical infection or inflammation." (PMID 28009810, 2016). "CRP and WBC counts are usually followed during the treatment of serious infections such as SAB." (PMID 27182730, 2016). "induce a different systemic inflammatory response is in line with data in the literature and indicates that the serum CRP concentration does not necessarily reflect the extent of local infection." (PMID 28773989, 2016). "This study indicates that clinicians may consider PTX3 as a marker of infection on equal terms with PCT and that these markers are more reliable as prognostic markers of disease severity than is CRP in patients with NSTI." (PMID 26880104, 2016). "The data suggest that ICIS is a useful marker to predict probable or proven infection and its severity and is non-inferior in this respect to CRP and PCT." (PMID 27384242, 2016). "Most of the authors did not use any parameters as CRP or erythrocyte sedimentation to define that infections were eradicated but they only mentioned that infection was eradicated in all or a part of the patients." (PMID 26904683, 2016). "The data suggest that the ICIS is potentially useful for the prediction of infection and its severity in critically ill patients, non-inferiorly to CRP and PCT." (PMID 27384242, 2016). "Moreover, many of the molecular players related to atherosclerotic plaque formation, including C-reactive protein (CRP), LDL cholesterol, and fibrinogen, are protective against infection-related mortality." (PMID 27990156, 2016). "Conversely, when infection was defined using CRP only (without parasitaemia), all covariates were non-significant." (PMID 27391972, 2016). "Like other nonspecific markers of inflammation such as serum CRP, they did not discriminate TB from other infections." (PMID 27734027, 2016). "At this point it is important to remember that CRP is not a specific marker of infection; more than that, as an acute phase protein, it is primarily part of the innate immune response and its increase can occur in many different conditions." (PMID 27792135, 2016). "The lack of decline of CRP in 14 days or during the second week were neither prognostic nor markers of deep infection focus." (PMID 27182730, 2016). "A systematic review based on studies from hospital settings suggested that CRP levels < 20 mg/L provided the best rule out value for serious infections in children." (PMID 27716201, 2016). "In our study neither the absolute values of CRP nor its delta changes were able to indicate new onset infection." (PMID 27597981, 2016). "The accuracy of several biomarkers in the diagnosis and management of infection, namely VAP, have been evaluated repeatedly with soluble triggering receptor expressed on myeloid cells (sTREM-1), C-reactive protein (CRP) and procalcitonin (PCT) being the most frequently studied." (PMID 27076187, 2016). "As regards clinical progress, inflammatory markers such as WBC count and serum CRP level were not higher in R017 infections than in infections by other ribotypes, but 30-day mortality was marginally higher." (PMID 28002482, 2016). "Surprisingly, omentin serum levels did not correlate with markers of acute inflammation or infection like CRP or procalcitonin (PCT)." (PMID 27867249, 2016). "Another etiology considered was infection, given the finding of raised C-reactive protein; however, no infective source was identified." (PMID 26667003, 2015). "In the univariate analysis, levels of LBP, IL-10, IL-6 and CRP were compared between patients with and without infection." (PMID 25613713, 2015).
infection (continued). "Traditional inflammatory markers showed basically no predictive ability for infection (AUC for CRP at postoperative day 2 = 0.534, AUC for WBC at postoperative day 2 = 0.641)." (PMID 25793700, 2015). "Measurements of inflammatory markers such as erythrocyte sedimentation rate (ESR) or C-reactive protein (CRP) have high negative predictive values when normal, but they are poorly predictive of infection when elevated." (PMID 26181332, 2015). "Further work is currently being carried out to measure CRP levels in asymptomatic, slide negative infections detected by highly sensitive PCR." (PMID 26558692, 2015). "Bacterial burden was weakly correlated with the number of neutrophils in the ascitic fluid (rs = 0.5, p = 0.012), but did not correlate with serum markers of infection/inflammation (C reactive protein (p = 0.44) or procalcitonin (p = 0.52))." (PMID 25781164, 2015). "Our study noted increased CRP levels in over 90 % of cases of both THA and TKA infections." (PMID 25987902, 2015). "When there is a postoperative abnormal CRP response with no clear evidence of intercurrent infection or other inflammatory processes, close observation for signs of SSI and serial monitoring of laboratory parameters are considered to be important." (PMID 25888882, 2015). "Further, the cut-off values of >1.2447 and <2.2 for C4d/CR1 and serum CRP level, respectively, were 80% sensitive and 100% specific for the absence of infection in febrile SLE patients." (PMID 26273660, 2015). "However, neither of the other parameters had the ability to differentiate infection from surgical inflammation (p-value for interaction = 0.4 for WBC and 0.29 for CRP)." (PMID 25793700, 2015). "The levels of CRP in patients with infection were significantly higher than those without infection." (PMID 26498833, 2015). "In all studies, CRP measurement was performed in a standardized manner for study purposes and independent of clinical suspicion of infection, nor was clinical suspicion of infection documented." (PMID 25935447, 2015). "In the low CRP group, gram-positive, gram-negative, fungal, and polymicrobial pathogens accounted for 74.5, 19.0, 2.8, and 3.6 % of infections, respectively." (PMID 26259626, 2015). "CRP has to be carefully taken into account because this is a non specific inflammatory marker sensitive to many factors (trauma, stress, infection...)." (PMID 26177207, 2015). "Data for CRP, leucocyte count and haemoglobin were available in 168 cases of THA infection." (PMID 25987902, 2015). "We propose infection and/or inflammation to play a potential role in the pathogenesis (e.g. significantly higher rate of CAM after PEIC as compared to UIC and HIC and significantly higher CRP-levels)." (PMID 26121653, 2015). "Therefore, hospitalized cirrhotic patients with an elevated CRP concentration and NLR should be monitored carefully for the presence of infection." (PMID 26498833, 2015). "We greatly appreciated the recent research article by Park and colleagues in Critical Care showing that procalcitonin (PCT) is not superior to C-reactive protein (CRP) as a marker for infection in renal impairment." (PMID 26002320, 2015). "Infection was unlikely given the absence of fever, normal C-reactive protein and sterile blood cultures." (PMID 26519297, 2015). "In the univariate analysis, levels of LBP, IL-10, IL-6 and CRP significantly differed between patients who developed an infection and those who did not." (PMID 25613713, 2015). "Since CRP, being an acute phase protein, regularly increases non-specifically not just during infections but also after surgery, determining the CRP level is particularly suitable for monitoring development." (PMID 25987902, 2015). "Lab results of white blood cell count, erythrocyte sedimentation rate, and serum C-reactive protein did not suggest infection." (PMID 25767420, 2015).
infection (continued). "C-reactive protein (CRP) is an acute-phase protein with normal serum concentrations of less than 3 mg/L that increases during an inflammatory process, especially following severe infection." (PMID 26672961, 2015). "Appetite, acute phase C-reactive protein (CRP), erythrocyte sedimentation rate (ESR) and body temperature (Tem) indicative of systemic inflammation, were measured 3 weeks (wk17) and chest X-ray taken 6 weeks (wk20) post-AdHu5Ag85A boost and before infection." (PMID 26252520, 2015). "No risk factors were identified in the other patients despite two of them having no appropriate elevation of C-reactive protein during the acute-phase of infection." (PMID 25738983, 2015). "C-reactive protein (CRP) is a readily available and cheap laboratory parameter, that is widely used in clinical routine as the most important acute phase serum protein to monitor infection." (PMID 26248232, 2015). "Low or high levels of white blood cells (WBC) and C-reactive protein (CRP) may be present, reflecting, respectively, the subacute or acute character of the infection." (PMID 25386377, 2014). "Alternatively, the increases in CRP, and SAA could reflect the localized production of IL-6 in the liver, possibly as a site of infection, inflammation and/or tissue injury in the early acute Lyme phase." (PMID 24740099, 2014). "In patients without infection, CRP did not correlate with eGFR, while PCT was negatively correlated with eGFR." (PMID 25407928, 2014). "These authors could not found any differences between groups in other markers of infection such as WCC, CRP, IL-6 and body temperature." (PMID 25132018, 2014). "There was a high prevalence of inflammation/infection as illustrated by the fact that 41% of individuals had raised CRP values (>5 mg/L), and there was a significant correlation between CRP and ferritin (p = 0.023) but not with Hb." (PMID 24275120, 2014). "A prolonged elevation of CRP levels with no subsequent decrease precedes the detection of infection by one day on average." (PMID 25132018, 2014). "The concentrations of CRP, Hp and SAA were significantly increased after infection." (PMID 24734294, 2014). "These different responses, depending on the severity of infection, suggest that CRP would be a more valuable infection marker because CRP increases gradually, even in less severe infection, allowing for differential diagnosis of SIRS or no SIRS." (PMID 25407928, 2014). "In addition, the levels of WBC, neutrophils and CRP had decreased by Day 8, indicating that the rat CMC-pouch biofilm infection model was well established and close to mimicking clinical infectious biofilm conditions." (PMID 25551618, 2014). "Three patients from group E suffered from antibiotic-associated diarrhea caused by Clostridium difficile, which was cultured from stool samples.We also monitored the real time concentration of C-reactive protein (CRP), an early indicator of infection or inflammation, in the blood of each patient." (PMID 24990477, 2014). "Among patients without infection, CRP was not correlated with eGFR, while PCT was inversely correlated with eGFR." (PMID 25407928, 2014). "Serum C-reactive protein and more recently PCT have been proposed to monitor short- and long-term infection in the setting THA, but appropriate interpretation of their levels in the early postoperative period is not easy, because of the associated inflammatory condition." (PMID 24877114, 2014). "The lack of decrease in CRP levels in the post operative period is a predictor of post-operative infections in patients submitted to colorectal surgery." (PMID 25132018, 2014). "ESR can be influenced by extraneous factors such as medication usage and blood viscosity and CRP exhibits nonspecific elevation in response to tissue inflammation and infection." (PMID 24678735, 2014).
infection (continued). "CRP, sTLR2 and sTLR4 circulating concentrations were significantly higher in patients with infection compared with patients with non-infectious inflammation (groups A and B)." (PMID 25406630, 2014). "At that time, clinical signs of infection were absent and blood tests were in normal range (C-reactive protein (CRP) = 12 mg/L, leukocytes = 8.230/mm3, serum creatinine = 1.17 mg/dL)." (PMID 25374744, 2014). "One study suggested that the PCT was a valuable parameter for determining infection, but was no better than CRP in evaluating the infection severity." (PMID 25960877, 2014). "Both patients with and without proven infections were severely inflamed, i.e., all patients had serum procalcitonin and C-reactive protein levels above the normal range, and there was considerable overlap between the groups." (PMID 24642872, 2014). "In these situations, PCT offers better specificity than CRP for differentiating between some infections and APR secondary to the diseases activity, regardless of therapy with corticosteroids and immunosuppressive drugs." (PMID 23207551, 2013). "None of the infants with infection were severely sick or needed transfer to the intensive care nursery (CRP: median [25th–75th percentiles] 1.05 [0.8–2.4] mg/dL)." (PMID 23365583, 2013). "Thus CRP and SAP can both participate in protection from S. pneumoniae, a common and often fatal infection in the young and the elderly." (PMID 24167754, 2013). "Unexpectedly, parameters that represent the intensity of inflammation such as body temperature or CRP levels did not predict the treatment outcome of infection." (PMID 23369129, 2013). "Three patients with a serum hs-CRP level of more than 30 mg/L without overt clinical symptoms or signs of infection at enrolment were excluded from the final data analysis because of the exacerbations and oral antibiotics given in the following weeks." (PMID 24381758, 2013). "PCT should be considered as a better marker than CRP to distinguish between APR to infection and an active non-specific urticarial inflammation." (PMID 23207551, 2013). "CRP alone can be a good indicator of bacterial infection in preterm and term neonates even though it is sensitive in early infections but not specific." (PMID 23941472, 2013). "Although there are multiple causes for elevated CRP levels in ESRD population, many patients experience high serum CRP values without any visible signs of infection and/or inflammation." (PMID 23840952, 2013). "CRP is a nonglycated protein produced by human hepatocytes in response to infection, inflammation, or tissue damage." (PMID 24007461, 2013). "CRP concentrations were higher in cirrhotic patients with infection compared to cirrhotic patients without infection." (PMID 24286072, 2013). "IL-6 has also the highest sensitivity (89%) and negative predictive value (91%) at the onset of infection compared with other biochemical markers, including CRP, TNF, and E-selectin." (PMID 24570828, 2013). "Regrettably, the number of patients studied was limited (n = 8), and the delay for reoperation in case of uncontrolled infections was not reported, limiting the conclusions that can be drawn regarding the usefulness of CRP values in this particular population." (PMID 24286072, 2013). "C-reactive protein has been considered as an indicator for adverse postoperative course including both surgical and non-surgical complications as it responds to both infection and inflammation." (PMID 23409097, 2013). "These infants were clinically well without signs of infection and their CRP levels were between 0.62 and 2.0 mg/dL." (PMID 23365583, 2013). "Our study does not agree with the relation between rate of decline in CRP up to D7 during treatment for infection in the ICU and survival, since the change of CRP did not predict outcome." (PMID 23762396, 2013).